C19orf81 (chromosome 19 open reading frame 81)
Tractability: No criterion of Open Targets' tractability assessment is met for any kind of drug.
Gene: Protein-coding gene on chromosome 19 (50,648,792 to 50,659,310, forward strand). Ensembl gene ENSG00000235034.
Subcellular location (Human Protein Atlas): Aggresome; Vesicles
Genetic constraint (gnomAD): Loss-of-function variants: 19 observed, 20.85 expected, observed/expected ratio (o/e) 0.91, 90% interval 0.63 to 1.34. The upper end of that interval is the gene's LOEUF score, 1.34, which puts it in group 5 of 6, group 1 being the genes least tolerant of losing a copy. Missense variants: 287 observed, 271.82 expected, observed/expected ratio (o/e) 1.06, 90% interval 0.96 to 1.16. Synonymous variants: 108 observed, 108.43 expected, observed/expected ratio (o/e) 1, 90% interval 0.85 to 1.17.
Homologues: Orthologues: chimpanzee C19H19orf81 (98% identical), macaque C19H19orf81 (95% identical), pig C19orf81 (82% identical), dog C19orf81 (81% identical), rat C1h19orf81 (80% identical), mouse 1700008O03Rik (78% identical).